NR5A2 (nuclear receptor subfamily 5 group A member 2)
Diseases named in the same sentence as NR5A2 in open-access papers (continued):
Sharing a sentence is not in itself a finding about the gene and the disease.
metabolic syndrome (2 papers, 2023 to 2024). A cluster of metabolic risk factors for CARDIOVASCULAR DISEASES and TYPE 2 DIABETES MELLITUS. "However, the association of NR5A2 and exercise with metabolic syndrome remains unclear." (PMID 37053002, 2023). "No clinical specimen experiments were performed to verify the role of NR5A2 in the metabolic syndrome." (PMID 37053002, 2023). "The main results of this study were that NR5A2 expression was low in metabolic syndrome, and NR5A2 expression was up-regulated after exercise in patients with metabolic syndrome." (PMID 37053002, 2023). "However, the relationship between NR5A2 and exercise in improving metabolic syndrome is still unclear." (PMID 37053002, 2023). "NR5A2 can be used as a potential target for exercise to improve metabolic syndrome." (PMID 37053002, 2023). "Therefore, the study aimed to use bioinformatics to explore core genes of metabolic syndrome between before and after exercise, and animal experiments were used to verify the value of NR5A2 in the exercise curing metabolic syndrome." (PMID 37053002, 2023). "NR5A2 might be used as a potential target for exercise to improve metabolic syndrome." (PMID 37053002, 2023). "Therefore, it is speculated that exercise may improve metabolic syndrome by up-regulating the expression of NR5A2." (PMID 37053002, 2023). "Western blot analysis showed that NR5A2, CYP7A1, and CYP8B1 were lowly expressed in metabolic syndrome, and their expression levels were up-regulated after exercise (P < 0.05)." (PMID 37053002, 2023). "PIK3R2, STRA8, FLT1, DMRT1, FGF22, NR5A2, and FLT genes were up-regulated in metabolic syndrome after exercise." (PMID 37053002, 2023). "PIK3R2, STRA8, FLT1, DMRT1, FGF22, NR5A2, and FLT were up-regulated and PRDM14, POU5F1, and KDR were down-regulated in metabolic syndrome after exercise." (PMID 37053002, 2023). "After carrying out NR5A2 knockout or overexpression experiments, it was found that NR5A2 reduced the level of inflammation through CYP7A1/CYP8B1, and C/EBPβ-FASN-SCD1 reduced the level of apoptosis, thereby improving the metabolic syndrome." (PMID 37053002, 2023).
neuroblastoma (2 papers, 2016 to 2022). Neuroblastoma (NB) is the most common solid, extracranial childhood tumor. "By performing transcriptional assays with these constructs in N2A neuroblastoma cells, we verified that NR5A2 strongly induces the activity of Loc2-Prox1 promoter." (PMID 27447294, 2016).
non-alcoholic fatty liver disease (2 papers, 2020 to 2021). "Interestingly, a pro-inflammatory function of Nr5a2 deficiency is linked to non-alcoholic fatty liver disease." (PMID 34099014, 2021).
Alzheimer disease (1 paper, 2025). A progressive, neurodegenerative disease characterized by loss of function and death of nerve cells in several areas of the brain leading to loss of cognitive function such as memory and language. "Additionally, the orthologs of nhr-25(NR5A1 and NR5A2) and unc-62 (MEIS1, MEIS2, MEIS3) were linked to aging-related diseases such as dementia and Alzheimer’s disease." (PMID 40766245, 2025).
cervical squamous cell carcinoma (1 paper, 2022). A squamous cell carcinoma arising from the cervical epithelium. "NR5A2 and the key gene vimentin (VIM) were significantly co-expressed in cervical squamous cell carcinoma, and VIM was also significantly co-expressed with EMT signaling pathway genes." (PMID 36232920, 2022).
cutaneous squamous cell carcinoma (1 paper, 2024). "Nuclear receptor subfamily five group A member two (NR5A2) plays a key role in the development of many tumor types, while it is uncertain in cutaneous squamous cell carcinoma (cSCC)." (PMID 38358044, 2024). "Nuclear receptor subfamily five group A member two (NR5A2) has a critical role in the occurrence and progression of cutaneous squamous cell carcinoma (cSCC), and it may be played via the Wnt/β‐catenin, at the same time, knockdown of NR5A2 expression mediates the effect of cisplatin in cSCC." (PMID 38358044, 2024).
endometrial cancer (1 paper, 2022). Primary or metastatic malignant neoplasm involving the endometrium (mucous membrane that lines the endometrial cavity). "We showed significant abnormalities in the expression of cancer-promoting genes in tissues proximal to endometrial cancer, with higher expression of MYC, NR5A2, SNAI1, and TWIST1, in tumor-adjacent tissues than in tumors, which suggests field cancerization effect." (PMID 36140779, 2022). "NR5A2 is expressed in endometrial cancer cell lines, but its role in EC pathogenesis has not been revealed." (PMID 36140779, 2022).
endometrial disorder (1 paper, 2018). A non-neoplastic or neoplastic disorder that affects the endometrium. "Combined with our result, we could speculate that the dysregulated expression of Nr5a2 may be associated with PCOS-associated endometrial disorders." (PMID 30322386, 2018).
endometrioid adenocarcinoma (1 paper, 2022). An adenocarcinoma characterized by the presence of malignant glandular epithelial cells resembling endometrial cells. "In addition, the expression of MYC and CXCR2 in the tumor related to non-endometrioid adenocarcinoma and reduced the risk of recurrence, respectively, and higher NR5A2 expression in tumor-adjacent tissue increased the risk of death." (PMID 36140779, 2022).
hepatoblastoma (1 paper, 2024). Hepatoblastoma (HB) is a malignant hepatic tumor and is the most common pediatric liver cancer. "NR5A2 also promotes cell proliferation in hepatoblastoma, and the toxic effects of adriamycin on hepatoblastoma can be potentiated by the use of NR5A2 antagonists." (PMID 38358044, 2024).
idiopathic pulmonary fibrosis (1 paper, 2024). Idiopathic pulmonary fibrosis (IPF) is a nonneoplastic pulmonary disease that is characterized by the formation of scar tissue within the lungs in the absence of any known cause. "Applying Standigm ASKTM to idiopathic pulmonary fibrosis (IPF), a complex lung disease, we focused on genes (AMFR, MDFIC and NR5A2) identified through KG evidence." (PMID 38349059, 2024).
leiomyoma (1 paper, 2022). A well-circumscribed benign smooth muscle neoplasm characterized by the presence of spindle cells with cigar-shaped nuclei, interlacing fascicles, and a whorled pattern. "We showed significantly higher levels of NR5A2 (also known as LRH-1) in EC-adjacent tissues than in paired tumors and in endometrial samples from cancer-free leiomyoma patients." (PMID 36140779, 2022). "Noteworthy, in leiomyomas, a decreased expression of MYC and NR5A2 in tumors compared to the corresponding myometrium has also been observed." (PMID 36140779, 2022).
lipoma (1 paper, 2019). A benign, usually painless, well-circumscribed lipomatous tumor composed of adipose tissue. "Specifically, LPP (lipoma preferred partner/LIM domain containing preferred translocation partner in lipoma), TNS3 (Tensin 3) and NR5A2 (nuclear receptor subfamily 5 group A member 2) encode proteins important in cell adhesion and migration." (PMID 30621612, 2019).
lymph node metastasis (1 paper, 2014). "We found that NR5A2 rs3790843 polymorphism was significantly associated with the risk of GC when compared with regional lymph node metastasis and distant metastasis." (PMID 25514243, 2014). "Two variables (lymph node metastasis and NR5A2 rs3790844) were included in the regression model by stepwise selection of the covariant variables and rs3790844 SNP was shown to be an independent protective factor for GC with a 21.6% decreased risk (HR = 0.784, 95% CI = 0.646–0.951, p = 0.014)." (PMID 25514243, 2014). "In the dominant model, NR5A2 rs3790844 polymorphism was associated with significantly lower risk of death in the groups of patients with lymph node metastasis, no distant metastasis, diffuse type and no chemotherapy history (log-rank p < 0.05)." (PMID 25514243, 2014). "Additionally, in the stratified analysis, NR5A2 rs3790844 polymorphism was associated with significantly lower risk of death in the groups of female, tumor size >5 cm, lymph node metastasis, no distant metastasis, diffuse type and no chemotherapy history in the dominant model." (PMID 25514243, 2014).
prostate carcinoma (1 paper, 2025). A carcinoma that arises from epithelial cells of the prostate gland. "Liver receptor homolog-1 (LRH1/NR5A2), a nuclear receptor critical for steroidogenic gene expression, is implicated in prostate cancer progression through driving steroidogenic genes, but is poorly studied in breast cancer." (PMID 40544998, 2025).
psoriasis (1 paper, 2022). An autoimmune condition characterized by red, well-delineated plaques with silvery scales that are usually on the extensor surfaces and scalp. "Consequently, NR5A2 down-regulation might cause psoriasis via the activation of ‘MATURITY ONSET DIABETES OF THE YOUNG’, while its overexpression activated ‘FOLATE BIOSYNTHESIS’, ‘NOD LIKE RECEPTOR SIGNALING PATHWAY’, and ‘EPITHELIAL CELL SIGNALING IN HELICOBACTER PYLORI INFECTION’." (PMID 36685512, 2022). "Typically, ABCC5 (p = 0.0012), CISD1 (p= 3.9e−10) and TRIB2 (p < 2.22e−16) levels in psoriasis cases increased compared with healthy samples, whereas NR5A2 (p = 1.8e−13), PEBP1 (p < 2.22e−16) and PRKAA2 (p < 2.22e−16) levels decreased in psoriasis samples." (PMID 36685512, 2022). "Typically, CISD1 (p = 3.9e-10), TRIB2 (p < 2.22e−16), and ABCC5 (p=0.0012) levels among psoriasis cases increased compared with healthy controls, whereas PRKAA2 (p < 2.22e−16), ACSF2 (p = 3e−15), TIMM9 (p= 0.049), PEBP1 (p < 2.22e−16) and NR5A2 (p=1.8e−13) levels decreased among psoriasis cases." (PMID 36685512, 2022).
pulmonary fibrosis (1 paper, 2024). Chronic progressive interstitial lung disorder characterized by the replacement of the lung tissue by connective tissue, leading to progressive dyspnea, respiratory failure, or right heart failure. "We selected four genes (NR5A2, AMFR, MDFIC and AXIN) that were upregulated more than 2-fold in the pulmonary fibrosis mouse model compared with the levels in the control group." (PMID 38349059, 2024).
severe combined immunodeficiency (1 paper, 2020). Severe combined immunodeficiency (SCID) comprises a group of rare monogenic primary immunodeficiency disorders characterized by a lack of functional peripheral T lymphocytes resulting in early-onset severe respiratory infections and failure to thrive. "Mutations in PTPRC have been identified in patients with autosomal recessive severe combined immunodeficiency (SCID); while, pathogenic mutations in NR5A2 have not been reported for any Mendelian disease." (PMID 32248360, 2020).
steatosis (1 paper, 2024). Increased lipid within the cytoplasm of cells. "Hepatocyte-specific knockout mice of NR5A2 resulted in liver inflammation prior to the appearance of lipid droplets, which is in step with that inflammation may precede steatosis in certain instances." (PMID 39438459, 2024).
type 2 diabetes (1 paper, 2024). "Furthermore, Nr5a2 expression exhibited a significant decrease in the livers of BKS-db mice, which serve as a model of type 2 diabetes and NASH, as well as in the livers of mice induced by high-fat diet (HFD) alone or HFD combined with carbon tetrachloride (CCL4) treatment." (PMID 39438459, 2024).
cancer (42 papers, 2012 to 2025). A tumor composed of atypical neoplastic, often pleomorphic cells that invade other tissues. "Further, using the syngeneic and orthotopic lung transplantation model, we elucidated augmented cancer biological properties associated with Nr5a2 promotion of LLC‐SD self‐renewal." (PMID 30740909, 2019). "NR5A2 (rs3790843 and rs3790844) single nucleotide polymorphisms (SNPs) genotyping were examined in DNA samples, extracted from paraffin-embedded cancer tissue." (PMID 25514243, 2014). "While some mechanisms, such as Wnt signaling, ALDH1-associated resistance and immune escape ligands, were consistently reported across several cancers, others appeared tumour-specific, such as NR5A2-driven recurrence in PDAC or CD73-associated immune evasion in TNBC." (PMID 41561527, 2025). "By targeting NR5A2, our objective was to disrupt the regulatory circuitry governing cancer stemness and evaluate its translational applicability for the clinical management of CRC." (PMID 41214698, 2025). "Bicluster 1 CpGs were found enriched in binding regions of TFs including GRHL2, TFAP2C, FOXA1, ER, CEBPB and NR5A2, TFs known to be important in many cancer‐related functions such as proliferation, stemness and epithelial‐to‐mesenchymal transition (EMT)." (PMID 38671580, 2024). "Cpd3 and Cpd3d2, inhibitors of NR5A2, have also been proven to inhibit the malignant behavior of cancer cells by interfering with β‐catenin." (PMID 38358044, 2024). "Intriguingly, using sorted differentiated CD133–FLUO–cancer cells, overexpression of NR5A2 induced upregulation of CD133 and CXCR4, enhanced sphere formation, and, most importantly, markedly enhanced in vivo tumorigenicity." (PMID 38012687, 2023). "In contrast, overexpression of NR5A2 induced in vivo tumorigenicity of most differentiated cancer cells." (PMID 38012687, 2023). "By targeting NR5A2, we aimed to disrupt the cancer stemness network and evaluate its potential as a therapeutic strategy for PDAC." (PMID 38012687, 2023). "In differentiated cancer cells, we validated the previously reported p21-mediated antiproliferative effect of NR5A2 inhibition." (PMID 38012687, 2023). "A Schematic illustration of the role of NR5A2 in cancer stem cells versus differentiated cancer cells, along with the action of the NR5A2 inhibitor Cpd3." (PMID 38012687, 2023). "In line with these mRNA data, we found detectable NR5A2 protein levels in differentiated cancer cells." (PMID 38012687, 2023). "Of note, Cpd3 monotherapy had limited benefits, emphasizing the importance of combining NR5A2 inhibition with chemotherapy to target both cancer stem cells and the larger population of differentiated PDAC cells." (PMID 38012687, 2023). "Inhibition of NR5A2 led to a metabolic shift in cancer stem cells towards glycolysis, reducing their stemness features." (PMID 38012687, 2023). "On the other hand, NR5A2 overexpression in differentiated cancer cells shifted their metabolism toward oxidative phosphorylation." (PMID 38012687, 2023). "Higher TAc NR5A2 expression in patients with cancer cells infiltrating the tumor-adjacent tissue increased the risk of death (HR 50.0557, 95% CI [2.105–1190.448], p = 0.016)." (PMID 36140779, 2022). "More recent studies have shown that Nr5a2, the last one of the candidate genes in our study, controls the development of some types of cancer by promoting cancer cell proliferation by regulating cell cycle." (PMID 34034704, 2021). "Gene ontology (GO) analysis showed that several cancer-related GO terms were downregulated in NR5A2-silenced PANC-1 cells." (PMID 33850096, 2021).
cancer (continued). "Further, using the syngeneic and orthotopic lung transplantation model we established and characterized, we evaluated the impact of alterations in stem cell properties upon Nr5a2 interference observed in vitro on the cancer biology properties in vivo." (PMID 30740909, 2019). "Using siRNA-mediated silencing and an NR5A2 antagonist we demonstrate that NR5A2-mediated cancer cell survival is facilitated through augmentation of GATA6 and anti-apoptotic factor BCL-XL levels." (PMID 27586588, 2016). "Our survival analysis revealed that high NR5A2 expression in cancer tissues predicted an improved prognosis, which also supported its protective roles in PDAC development." (PMID 25742499, 2015). "NR5A2 has been proposed as a potential cancer marker due to its upregulation in tumors." (PMID 39438459, 2024). "Moreover, NR5A2 exhibited a protective role against cellular stimuli and promoted cell proliferation, thereby acting as a crucial molecule in cancer cells." (PMID 39438459, 2024). "In differentiated cancer cells, NR5A2 promotes cell proliferation by inhibiting CDKN1A." (PMID 38012687, 2023). "Therefore, we performed a comprehensive study to define the cancer cell phenotype-specific role of NR5A2 in PDAC and explored its potential as a therapeutic target in a large-scale preclinical study." (PMID 38012687, 2023). "Furthermore, microRNA-219-5p and microRNA-136 have been demonstrated to regulate the expression level of NR5A2 in cancer cells." (PMID 33850096, 2021). "Besides, transcriptome RNA sequencing (RNA-Seq) was performed to explore the cancer-promoting effects of NR5A2, we found that GDF15 is a component of multiple down-regulated tumor-promoting gene sets after NR5A2 was silenced." (PMID 33850096, 2021). "LRH‐1 (also known as NR5A2) belongs to the nuclear receptor (NR) family which contains many transcription factors that regulate diverse biological processes such as embryonic development, differentiation, metabolism, and cancer." (PMID 32037723, 2020). "To investigate whether Nr5a2 and Nanog expressions have clinical implications in human cancers, we examined their expressions in NSCLC paraffin‐embedded tissues with distinct TNM stage by RT‐qPCR." (PMID 30740909, 2019). "Thus, here, we would like to propose a tumour suppressor function for NR5A2 specific for nervous system-related cancers via induction of p16Ink4a and p15Ink4b genes." (PMID 27447294, 2016). "The clinical and cohort significance of NR5A2-mediated transcriptional activities indicates that it may have a significant role in attenuating grade development and cancer related signal transduction pathways." (PMID 26366408, 2015). "However, no statistical differences were observed in the relative expression of NR5A2 between cancer tissues and adjacent controls." (PMID 24204738, 2013). "Nuclear receptor subfamily 5, group A, member 2 (NR5A2), a gene associated with cell cycle and cancer invasion, was predicted to harbor an 8-mer site that matches the complementary sequence of the miR-139-5p seed region based on a miRNA target prediction tool (TargetScan Release 6.0)." (PMID 24204738, 2013). "In addition, NR5A2 can modulate chemosensitivity of cancer cells to cisplatin." (PMID 36303447, 2022). "Therefore, NR5A2-mediated cancer cell survival may form the basis of potential complementary therapeutic approaches if suitably targeted." (PMID 27586588, 2016). "The specific effects of SR1848, which inhibits NR5A2, ON1231320 or BI2536, which inhibits PLK2, and blebbistatin, which inhibits MYH10, were further validated in cancer cell lines." (PMID 39814695, 2025). "This study aimed to define the role of NR5A2 in CRC, particularly in the context of cancer stem cells (CSCs)." (PMID 41214698, 2025).